EZH2 (enhancer of zeste 2 polycomb repressive complex 2 subunit)
Diseases named in the same sentence as EZH2 in open-access papers (continued):
Sharing a sentence is not in itself a finding about the gene and the disease.
Hypertension (2 papers, 2022 to 2024). The presence of chronic increased pressure in the systemic arterial system. "EZH2 influences the development of hypertension by regulating VSMC proliferation, migration and phenotypic transition." (PMID 38994197, 2024). "Inhibitors of EZH2 have shown considerable potential in enhancing vascular function and treating CVDs, including hypertension and AS." (PMID 38994197, 2024). "Therefore, an in-depth study of the mechanism of EZH2 in VSMCs dysfunction is necessary for better understand and treat hypertension." (PMID 38994197, 2024). "Hence, targeting EZH2 in VSMCs maybe a promising approach for treating diseases like AS and hypertension characterized by abnormal VSMC proliferation, migration and vascular remodeling." (PMID 38994197, 2024). "Targeting EZH2 via modulating miR-26a expression can reduce VSMC proliferation and inhibit vascular remodeling in hypertension." (PMID 38994197, 2024).
hyperuricemia (2 papers, 2022 to 2023). An abnormally high level of uric acid. "A recent study has also proved that EZH2 inhibition could relieve hyperuricemia-induced renal injury and fibrosis, suggesting its promise as a potential strategy for the treatment of hyperuricemia-induced CKD." (PMID 36050772, 2022).
immune-deficient disorders (2 papers, 2022). "Our findings suggest that PRC2-mediated suppression under homeostatic and inflammatory conditions limits ASC differentiation and that this can be therapeutically exploited through inhibition of Ezh2 to amplify protective antibody responses in various human immune-deficient disorders." (PMID 35831623, 2022).
immuno deficiency (2 papers, 2017 to 2022). "GSEA pathways indicated that Cell cycle, DNA replication, Primary immuno deficiency, Metabolism were all involved in the association with EZH2 expression." (PMID 36195655, 2022).
injury (2 papers, 2022 to 2023). Damage inflicted on the body as the direct or indirect result of an external force, with or without disruption of structural continuity. "In short, by regulating the production of pro-inflammatory mediators, EZH2 regulates peripheral and central sensitization induced by nerve injury." (PMID 37048131, 2023). "Increased expression of CGRP and microglial activation were temporally associated with increased EZH2 and H3K27me3 expression in the spinal cord in neuropathic rats induced by CCI on days 1 to 10 after nerve injury." (PMID 37048131, 2023).
ischemia (2 papers, 2021 to 2024). A hypoperfusion of the BLOOD through an organ or tissue caused by a PATHOLOGIC CONSTRICTION or obstruction of its BLOOD VESSELS, or an absence of BLOOD CIRCULATION. "Our data showed that, specifically after ischemia, Ezh2 knockdown shifted the balance between self-renewal and differentiation toward differentiation in adult dentate gyrus." (PMID 38676810, 2024). "Because the pyramidal neurons of CA1 region were lost after transient ischemia which is known as “delayed neuronal death,” Ezh2 signals of the ischemia groups were also lost in the CA1 region." (PMID 38676810, 2024). "To evaluate the effect of Ezh2 knockdown on neurogenesis after global ischemia, we used RNA-mediated gene silencing system delivered by AAV vector into DG." (PMID 38676810, 2024). "Recently, it was demonstrated that EZH2 can regulate renal injury by inducing oxidative stress as evidenced by the fact that EZH2 inhibition blocked the production of NOX4 dependent ROS through the ALK5/Smad2/3 signal pathway in an animal model of ischemia/reperfusion-induced AKI." (PMID 33679454, 2021). "Furthermore, the number of neural stem cells of SGZ significantly decreased in the ischemia plus negative shRNA group compared to the control, and further decreased in the ischemia plus Ezh2 knockdown group." (PMID 38676810, 2024). "Remarkably, we found that Ezh2 shRNA reduced the increment of EdU-positive cells after transient forebrain ischemia (33.0 ± 5.8, not significant vs control group, p < 0.05 vs negative shRNA + ischemia group)." (PMID 38676810, 2024). "Furthermore, Ezh2 knockdown did not affect the distance from SGZ to proliferated cells in the sham-operated controls but significantly increased in the ischemia groups." (PMID 38676810, 2024). "On the other hand, Ezh2 shRNA + ischemia group (19.8 ± 2.5 μm) showed significantly longer distance from SGZ compared to the control (p < 0.001) and even negative shRNA + ischemia (p < 0.05) groups." (PMID 38676810, 2024).
ischemic cardiomyopathy (2 papers, 2019 to 2023). Ischemic cardiomyopathy is a cardiomyopathy in which a weakness in the muscle of the heart due to inadequate oxygen delivery to the myocardium with coronary artery disease being the most common cause. "Human ischemic cardiomyopathy is defined by DNA hypermethylation, methyltransferase EZH2 induction, and transcription factor KLF15 suppression." (PMID 30089854, 2019). "Our data are consistent with a recent study highlighting increased cardiac EZH2 expression, as well as cardiac enrichment of known gene targets of EZH2, such as KLF15, in ischemic cardiomyopathy patients." (PMID 37491334, 2023).
Kabuki syndrome (2 papers, 2022 to 2025). Kabuki syndrome (KS) is a multiple congenital anomaly syndrome characterized by typical facial features, skeletal anomalies, mild to moderate intellectual disability and postnatal growth deficiency. "To further validate the specificity of the BOS DNAm signature generated, we classified three cohorts of individuals with Sotos, Weaver, and Kabuki syndromes, caused by variants in genes encoding the epigenetic regulators, NSD1, EZH2, and KMT2D, respectively." (PMID 35361921, 2022).
kidney injury (2 papers, 2024 to 2025). Trauma to the kidney. "This research sought to assess the possible impact of the SOX4/EZH2 axis on ferroptosis in the pathogenesis of CaOx-induced kidney injury and evaluate the protective effect of EZH2 inhibition." (PMID 38169402, 2024). "Our study demonstrated that the upregulation of enhancer of zeste homolog 2 (EZH2)-mediated ferroptosis facilitates CaOx-induced kidney injury." (PMID 38169402, 2024). "Moreover, the protective effect of EZH2 inhibition with 3-DZNep has been demonstrated in kidney injuries." (PMID 38169402, 2024).
liver cirrhosis (2 papers, 2013 to 2014). "Out of all HCC tissues, 90% (150/167) were immunopositive for EZH2, whereas the adjacent normal tissues and liver cirrhosis tissues were immunonegative or weak for EZH2." (PMID 25226601, 2014).
malignant meningiomas (2 papers, 2013 to 2022). "Our research indicates a direction of EZH2 inhibitors combined with PD-1 immunotherapy for malignant meningiomas in the future." (PMID 36532284, 2022). "DNMT1 has been previously shown to interact with PRC component EZH2 and to methylate PRC targeted genomic regions, therefore increased DNMT1 levels in malignant meningiomas may be recruited to PRC-targeted CpG islands and induce focal DNA hypermethylation." (PMID 23349797, 2013).
metastatic colorectal cancer (2 papers, 2015 to 2017). "In conclusion, we found that EZH2 expression was associated with survival in patients with metastatic colorectal cancer who underwent surgical treatment and chemotherapy with anti-EGFR antibodies." (PMID 28147317, 2017). "The C/C genotype for the EZH2 rs3757441 single-nucleotide polymorphism (SNP) is linked with poor prognosis in metastatic colorectal cancer (CRC), but molecular and pathological characterization of this SNP is lacking." (PMID 26553291, 2015). "Future large and independent studies are necessary for confirming the correlation between low EZH2 expression and unfavorable prognosis in patients with metastatic colorectal cancer who have received anti-EGFR therapy." (PMID 28147317, 2017). "Therefore, we conducted this study to assess the relation between EZH2 expression and clinical outcomes in patients with metastatic colorectal cancer treated with anti-EGFR therapeutics." (PMID 28147317, 2017).
microcephaly (2 papers, 2025). A congenital or acquired developmental disorder in which the circumference of the head is smaller than normal for the person's age and sex. "Our findings highlight a critical role for Asxl1 in maintaining NSC survival and neurogenesis through its interaction with EZH2, providing insights into the mechanisms underlying microcephaly and developmental disorders associated with ASXL1 mutations." (PMID 40276524, 2025). "In the KO mice for essential components of the PRC2 complex, Ezh2 and Eed, the balance between self-renewal and differentiation in NPCs shifted towards differentiation, resulting in the reduced number of neuron production and microcephaly-like phenotype." (PMID 39815005, 2025).
microphthalmia (2 papers, 2018 to 2021). Congenital or developmental anomaly in which the eyeballs are abnormally small. "Some of the Ezh2 null mice displayed microphthalmia: the eye was approximately 2/3 the size of that in the wild-type littermates (n = 5/10)." (PMID 30169530, 2018). "Ezh2 directly or indirectly influences retinal cell differentiation and maturation as conditional knockout of Ezh2 in retinal progenitor cells results in microphthalmia, reduction in postnatal progenitor proliferation, and accelerated differentiation of rods and Muller glia." (PMID 33563331, 2021). "Second, the Ezh2 null pups displayed absence of outer ear and microphthalmia." (PMID 30169530, 2018).
mood disorder (2 papers, 2019 to 2022). A cognitive disorder a disturbance in which the person's mood is hypothesized to be the main underlying feature. "Considering altered expression of Ezh2 and miR-137 in patients with mood disorders, our results suggest that the dysregulation of miR-137-Ezh2 axis might contribute to mood disorders in humans." (PMID 31736707, 2019).
myeloid hemopathies (2 papers, 2016 to 2021). "EZH2-inactivating mutations are not restricted to myeloid hemopathies." (PMID 26497210, 2016).
NUT carcinoma (2 papers, 2014 to 2025). "For instance, combining CDK4/6 inhibitors or EZH2 inhibitors with BET inhibitors has demonstrated synergy, and currently, new phase I combination trials are being tested in NUT carcinoma in the USA (NCT05372640, NCT05019716, NCT05488548)." (PMID 39863772, 2025).
oropharyngeal carcinoma (2 papers, 2016 to 2017). Carcinoma, predominantly squamous cell, arising from the epithelial cells of the oropharynx. "We are in the process of developing a specific clinical protocol for patients with a confirmatory biopsy of HPV -oropharyngeal carcinoma (p16INK4a+/EZH2+) with high Ki-67 expression and mitotic progression." (PMID 28818106, 2017). "Our study showed that p16INK4a-HPV infection is associated with the E6 and E7 oncogenes and with the expression of EZH2, Ki-67, and mitotic progression in oropharyngeal carcinoma." (PMID 28818106, 2017). "This is the first study using clinical specimens to demonstrate EZH2 protein expression in oropharyngeal carcinoma (OPC)." (PMID 28818106, 2017). "There is morphoproteomic and mRNA evidence of the association of p16INK4a-HPV infection with the E6 and E7 oncogenes and the expression of EZH2, Ki-67 and mitotic progression in oropharyngeal carcinoma." (PMID 28818106, 2017).
parathyroid cancer (2 papers, 2021). "Taken together, PVT1 may participate in parathyroid cancer development through EZH2 pathway." (PMID 33910638, 2021).
Parkinson disease (2 papers, 2015 to 2020). A progressive degenerative disorder of the central nervous system characterized by loss of dopamine producing neurons in the substantia nigra and the presence of Lewy bodies in the substantia nigra and locus coeruleus. "Previous studies also found the role of EZH2 for DNA hypermethylation in the epigenetic inhibition of the dopamine receptor D4 (DRD4), which is important for neurodegenerative disease such as HD and Parkinson’s disease." (PMID 26636336, 2015).
Pca (2 papers, 2016 to 2021). "In PCa, EZH2 expression is significantly elevated and is associated with increased proliferation activity and metastatic capability." (PMID 34199763, 2021). "Recently, increased EZH2 expression in PCa was associated with metastatic recurrence following external beam radiotherapy." (PMID 34199763, 2021). "As a potential biomarker, EZH2 expression in diagnostic prostate biopsies has been found to be an independent predictor of outcome patients with PCa." (PMID 34199763, 2021). "EZH2 binds the hepatocyte nuclear factor 1β (HNF1B) locus and suppresses its expression in PCa cell lines; consistently, a reverse correlation between EZH2 and HNF1B expression is present in clinical samples." (PMID 34199763, 2021). "When used in line with antiandrogen therapy, EZH2 inhibitors may contribute to improved outcomes in both early- and late-stage mCRPC patients, through their antitumoral activity and ability to re-sensitize hormone-refractory Pca." (PMID 34199763, 2021). "Elevated EZH2 expression is also correlated with development of CRPC and even neuroendocrine differentiation, but the mechanisms via which EZH2 enhances PCa progression are still unclear." (PMID 34199763, 2021). "EZH2 inhibition/depletion has been shown to enhance the efficacy of enzalutamide in enzalutamide-resistant PCa cells." (PMID 34199763, 2021). "Links with novel EMT regulators have also been revealed; the lncRNA MALAT1 enhances the oncogenic activities of EZH2, acting as a crucial RNA cofactor, in castration-resistant PCa." (PMID 34199763, 2021). "In several tumors, including PCa, EZH2 overexpression was found to positively correlate with disease progression and poorer prognosis." (PMID 34199763, 2021). "Under these circumstances, inhibition of EZH2 would expectantly suppress PCa cell proliferation and invasion in vivo and in vitro." (PMID 34199763, 2021). "Indeed, EZH2 inhibition has been shown to restore AR expression and sensitivity to antiandrogen therapy in preclinical models of advanced PCa, suggesting epigenetic reprogramming as a promising approach to bypass antiandrogen therapy resistance." (PMID 34199763, 2021). "Moreover, targeting Ezh2 could overcome docetaxel resistance in PCa cells, by suppressing Doc-induced cancer stem-cell populations." (PMID 34199763, 2021). "Strong links between EZH2 and EMT-mediated cell plasticity have been lately highlighted in PCa." (PMID 34199763, 2021).
pituitary cancer (2 papers, 2015 to 2023). A primary or metastatic malignant neoplasm affecting the pituitary gland. "The overexpression of EZH2 is consistent in various types of solid tumors and associated with poor prognosis in prostate, breast, bladder, lung and pituitary cancers." (PMID 37175580, 2023). "Therefore, it seems to be reasonable to assume that mainly pituitary tumors with elevated proliferation rates and high EZH2 expression (e.g. atypical PA and pituitary carcinomas) may benefit from its inhibition." (PMID 26593398, 2015).
plasmacytoma (2 papers, 2018 to 2020). Plasmacytoma is a localized mass of neoplastic monoclonal plasma cells that represents approximately 5% of all plasma cell neoplasms. "Likewise, it has also been indicated that lncRNA plasmacytoma variant translocation 1 can recruit EZH2 to elevate the accumulation of H3K27me341, which further validates our results." (PMID 32157157, 2020).
pleural mesothelioma (2 papers, 2022 to 2025). A neoplasm that arises from the mesothelial cells of the pleura. "Recent study reports that EZH2 inhibitor EPZ-6438 triggers malignant pleural mesothelioma cells to express high level of different monocytes chemoattractants, including CCL2 and CSF1, which lead to increased monocytes recruitment in tumor spheroids as well as M2 TAMs differentiation." (PMID 36038549, 2022). "We previously demonstrated that in BAP1-proficient pleural mesothelioma cells, CDKN2A is critical for mediating the response to selective EZH2 inhibition and highlighted a complex interplay between epigenetic regulation and the tumor immune microenvironment." (PMID 41226368, 2025).
pneumonia (2 papers, 2021 to 2024). An acute, acute and chronic, or chronic inflammation focally or diffusely affecting the lung parenchyma, caused by an infection in one or both of the lungs (by bacteria, viruses, fungi, or mycoplasma.). "We next set out to define the role of EZH2 in neutrophil protection from pneumonia by using an adoptive transfer model, in which we restored EZH2 intact neutrophils to LysM‐Ezh2fl/fl targeted animals." (PMID 34464475, 2021). "Furthermore, it has been observed that METTL3 downregulation can reduce m6A modification on the enhancer of zeste homolog 2 (EZH2) mRNA, thereby decreasing EZH2 expression and inhibiting inflammation and cell apoptosis in a pneumonia cell model." (PMID 38757482, 2024).
polycythemia vera (2 papers, 2022 to 2025). "Other mutations described in polycythemia vera include ASXL1 and EZH2." (PMID 35456443, 2022).
posterior fossa ependymoma (2 papers, 2016 to 2025). A high grade ependymoma that is located within the posterior fossa. "As it was recently suggested, posterior fossa ependymomas expressing EZH2 may have the same epigenetic signature as the PFA tumors connected with CpG island methylator phenotype." (PMID 27390862, 2016).
rectal tumors (2 papers, 2019 to 2023). "SDR16C5 has been found to be upregulated in KRAS-mutant rectal tumors compared to KRAS wild-type, and increased SIRPA may be indirectly linked to mutant KRAS through the overexpression of the EZH2 polycomb complex." (PMID 37141389, 2023). "With respect to the analysis of EZH2 expression in CRC, the use of various scoring systems, different cutoff values, or mixed patient cohorts of colon and rectal tumors make it very difficult to compare the different studies and question the clinical application of EZH2 as a reliable biomarker." (PMID 31317325, 2019).
renal medullary carcinoma (2 papers, 2025). "Here we present an unusual case of a patient with renal medullary carcinoma with metastasis to the brain following treatment which included tazemetostat, an EZH2 inhibitor." (PMID 39833894, 2025). "EZH2 inhibitors have demonstrated promise for RCCs with INI1 (SMARCB1) loss, such as renal medullary carcinoma." (PMID 39858107, 2025).
serous carcinoma (2 papers, 2023 to 2025). "High expression of EZH2 was almost always present (89% for both endometrioid and serous carcinomas)." (PMID 38146588, 2023). "EZH2 immunopositivity showed a statistically significant correlation with higher tumour grade (p = 0.009) and more aggressive histological subtypes such as serous carcinoma (p = 0.013)." (PMID 40310411, 2025).
small cell carcinoma of the ovary (2 papers, 2022 to 2025). "Histone deacetylase (HDAC) inhibitors and EZH2 inhibitors have been shown to synergize in BRG1-deficient small cell carcinoma of the ovary, hypercalcemic type cells through increased H3K27 acetylation." (PMID 35326450, 2022).
soft tissue neoplasm (2 papers, 2016 to 2021). A benign, intermediate, or malignant neoplasm that arises from the soft tissue. "Similar tendency for the higher rate of EZH2 and EED amplification was found for skin, prostate, and soft tissue tumors." (PMID 34202528, 2021). "ES are bone or soft tissue neoplasms with a prominent immature stemness phenotype maintained by epigenetic repressors BMI1 and EZH2." (PMID 27363011, 2016).
status epilepticus (2 papers, 2015 to 2019). Status epilepticus is defined as a continuous seizure lasting more than 30 min, or two or more seizures without full recovery of consciousness between any of them. "A transient inhibition of EZH2 immediately after status epilepticus (SE) robustly increases spontaneous seizure burden weeks later." (PMID 31891591, 2019). "Here, we explored the transcriptional response of genes associated with polycomb repressive complex (PRC) 1 (Ring1A, Ring1B, and Bmi1) and PRC2 (Ezh1, Ezh2, and Suz12), as well as additional transcriptional regulators Sirt1, Yy1, and Yy2, in a mouse model of status epilepticus (SE)." (PMID 25806020, 2015).